NLGN1 (neuroligin 1)
Diseases named in the same sentence as NLGN1 in open-access papers (continued):
Sharing a sentence is not in itself a finding about the gene and the disease.
depression (8 papers, 2015 to 2025). "The top associated variant rs73182688 in NLGN1 in this study is nominally associated with BMI (p = 0.0006), depression (p = 0.004 in FinnGen R5), and personality disorder (p = 0.004 in FinnGen R5)." (PMID 36253440, 2023). "NLGN1 was also implicated in a preclinical model of depression." (PMID 36253440, 2023). "In addition, SNS reversed the reduced expression of PSD95, SYN, neuroligin-1 and GAP43 proteins in the DRN brain region MS co-CUMS model, in line with previous depression models and some antidepressant research." (PMID 40469980, 2025).
Alzheimer disease (6 papers, 2019 to 2024). A progressive, neurodegenerative disease characterized by loss of function and death of nerve cells in several areas of the brain leading to loss of cognitive function such as memory and language. "Clinically, NLGN1 genetic variants are associated with disorders, such as ASDs, Alzheimer's disease (AD) and post-traumatic stress disorder (PTSD)." (PMID 31185809, 2019). "Patients with Alzheimer's disease or mice with Alzheimer's disease have decreased neuroligin 1 in their brain." (PMID 34882968, 2022). "Triptolide and tripchlorolide exert beneficial effects on synapses in Alzheimer’s disease mice, and the underlying mechanism may be related to DNA methylation, for the compounds can inhibit the DNA methylation of Nlgn1 promoter in the hippocampus, and thus increase the expression of gene Nlgn1." (PMID 34950039, 2021).
epilepsy (6 papers, 2014 to 2025). A brain disorder characterized by episodes of abnormally increased neuronal discharge resulting in transient episodes of sensory or motor neurological dysfunction, or psychic dysfunction. "Chromosomal partial deletion of NLGN1 was association with severe intellectual disability, seizures disorder." (PMID 26674772, 2015).
Cognitive impairment (4 papers, 2020 to 2025). Abnormal cognition is characterized by deficits in thinking, reasoning, or remembering. "In conclusion, many studies have described the possible implication of Nlgn1 dysfunction in cognitive disorders, which make the protein an interesting synaptic biomarker candidate to study." (PMID 33522967, 2021). "Nlgn1 has been connected to cognitive disorders, while others have investigated specifically the possible involvement of Nlgn1 in AD and neurodegenerative conditions." (PMID 33522967, 2021). "Nlgn1 has been connected to cognitive disorders, and specifically to AD, as target of the synaptotoxic effect of amyloid-β (Aβ) oligomers and Aβ fibrils." (PMID 33522967, 2021). "We found that hippocampal NLGN1 was decreased in patients with AD in comparison to patients with mild cognitive impairment and control subjects." (PMID 32332783, 2020). "We found that aMCI individuals have lower levels of NLGN1 in the hippocampus compared to age-matched CTRL without cognitive impairment (p < 0.001)." (PMID 32332783, 2020).
obsessive-compulsive disorder (4 papers, 2017 to 2023). A disorder characterized by the presence of persistent and recurrent irrational thoughts (obsessions), resulting in marked anxiety and repetitive excessive behaviors (compulsions) as a way to try to decrease that anxiety. "Sanger sequencing confirmed that the NLGN1 variant (P89L) was inherited from the mother, who was not diagnosed with ASD but suffered from obsessive-compulsive disorder (OCD) and anxiety disorder." (PMID 28841651, 2017).
post-traumatic stress disorder (4 papers, 2016 to 2022). An anxiety disorder precipitated by an experience of intense fear or horror while exposed to a traumatic (especially life-threatening) event. "NLGN-1 has been associated with post-traumatic stress disorder (PTSD) in humans." (PMID 35574490, 2022).
colon cancer (3 papers, 2021 to 2022). "First, we have tried to mine the GSE39582 and GSE24551 to perform the comparison of NLGN1 expression between normal versus colon cancer specimens." (PMID 34340665, 2021). "We thus investigated the expression of NLGN1 in CRC at the protein level by immunohistochemistry (IHC) on tissue microarrays (TMA) and on a subset of colon cancers available in our Institution." (PMID 36056393, 2022).
colorectal cancer (3 papers, 2021 to 2025). A primary or metastatic malignant neoplasm that affects the colon or rectum. "The clinical value of NLGN1 in colorectal cancer (CRC) is not clear." (PMID 34340665, 2021).
diabetes (3 papers, 2021 to 2024). "A recent study discovered that the upregulation of QKI-7 enhances mRNA degradation of CD144, neuroligin 1 (NLGN1), and TNF-α-stimulated gene/protein 6 (TSG-6) in diabetes, altogether contributing to diabetic endothelial dysfunction." (PMID 35597446, 2022).
memory impairment (3 papers, 2015 to 2022). "We first investigated the implication of NLGN1 specifically in Aβo-driven memory impairment using assessments of spatial and working memory, selected for their dependency on the hippocampus." (PMID 32332783, 2020). "Since neuroinflammation has been considered a major mechanism for POCD and neuroinflammation impairs learning and memory, a possible pathway for POCD is surgery‐neuroinflammation‐HDAC activation‐neuroligin 1 decrease‐synapse impairment‐learning and memory impairment." (PMID 34882968, 2022). "Firstly, Nlgn1 KO mice injected with Aβo1-42 were the only group showing memory impairment in SOR." (PMID 32332783, 2020). "In addition, we tested whether the absence of NLGN1 aggravates memory impairment and neuronal losses caused by Aβo1-42 using chronic hippocampal Aβo1-42 injections combined to immunohistochemistry and assessments of spatial and working memory." (PMID 32332783, 2020).
colorectal tumors (2 papers, 2022). "Here we show that NLGN1 is expressed in human colorectal tumors, including clusters of aggressive migrating (budding) single tumor cells and vascular emboli." (PMID 36056393, 2022).
fragile X syndrome (2 papers, 2023 to 2024). A genetic syndrome caused by mutations in the FMR1 gene which is responsible for the expression of the fragile X mental retardation 1 protein. "Translation of the mRNAs for NLGN1, NLGN2, and NLGN3 is negatively regulated by Fragile X mental retardation protein (FMRP), loss of this translational repressor, FMRP, leads to Fragile X syndrome, associated with ASD." (PMID 37807632, 2023).
glioblastoma (2 papers, 2021 to 2024). The most malignant astrocytic tumor (WHO grade IV). "Cleavage of NLGN1 and NLGN3 has been previously studied with important functional implications of the extracellular domain (ECD) cleavage byproduct of NLGN3 serving as a mitogen for glioblastoma in the brain." (PMID 39766868, 2024).
mood disorder (2 papers, 2021 to 2022). A cognitive disorder a disturbance in which the person's mood is hypothesized to be the main underlying feature. "We have recently shown, through a deep cognitive characterisation using a series of touchscreen-based assays, that while associative learning was not impacted due to loss of Nlgn1, motivated behaviour and cost-reward processing was consistently disrupted, having implications for mood disorders." (PMID 34690694, 2021). "In conclusion, to the best of our knowledge, our study is the first to identify neuroligin 1 and its regulator INFS as potential targets for treating prenatal glucocorticoid-induced neurogenesis defects and memory/mood disorders." (PMID 35562616, 2022).
pancreatic cancer (2 papers, 2022 to 2025). "Through immunohistochemistry on human tissue microarrays, we showed that NLGN1 is expressed by prostatic and pancreatic cancer tissues in discrete stages and tumor districts." (PMID 35053395, 2022). "Probably, the highly aggressive nature and rapid progression of pancreatic cancer, and the paucity of surgical samples at low stages, makes it difficult to isolate the window of expression of NLGN1 in this disease." (PMID 35053395, 2022). "Our study provides the first widespread analysis of NLGN1 expression in prostatic and pancreatic cancer at the tissue level." (PMID 35053395, 2022). "The expression pattern in the prostate suggests that the expression of this protein is present during the mildly aggressive phases of progression, and falls at higher stages, which is in agreement with the low expression of NLGN1 in pancreatic cancer at all stages that we analyzed." (PMID 35053395, 2022). "In this report, we asked whether the synaptic protein neuroligin 1 (NLGN1) was expressed by prostatic and pancreatic carcinomas; in addition, given the tendency of these tumors to interact with nerves, we asked whether NLGN1 played a role in this process." (PMID 35053395, 2022).
prostate carcinoma (2 papers, 2021 to 2025). A carcinoma that arises from epithelial cells of the prostate gland. "We show NRXN1 and NLGN1 expression in epithelial, endothelial, immune and neuronal cells in prostate cancer using cyclic immunofluorescence." (PMID 34911933, 2021). "Our cyclic IF analysis revealed the spatial distribution of NRXN1 and NLGN1 in prostate cancer and identified cell-type specific expression patterns for both proteins." (PMID 34911933, 2021). "To determine the expression pattern of NRXN1 and NLGN1 in prostate cancer across different cell types, we performed cyclic IF staining on tissue sections from eight patients in our cohort, using cell-type specific markers." (PMID 34911933, 2021). "We observe NRXN1 and NLGN1 are expressed in blood vessels in the prostate cancer tissue sections." (PMID 34911933, 2021). "The expression and function of NRXN1 and NLGN1 in prostate cancer have not been characterized before." (PMID 34911933, 2021).
tauopathies (2 papers, 2020 to 2021). "The dramatic reduction of Nlgn1 seen in the brain extracts of tauopathies warrants further investigation regarding the potential use of Nlgn1 as a biomarker for these neurodegenerative diseases." (PMID 33522967, 2021). "Although the focus of the study was on AD pathology, we also investigated the protein in different tauopathies, to explore Nlgn1 correlation to tau spreading." (PMID 33522967, 2021). "We initially focused on AD, but then expanded the study of Nlgn1 changes in brain to a group of primary tauopathies to be able to investigate Nlgn1 in relation to both Aβ and tau." (PMID 33522967, 2021). "However, Nlgn1 levels showed the greatest reduction in frontal grey matter of different tauopathies, which raises the interest for further investigations in the CSF of these patients and in possible roles of Nlgn1 shedding in primary tau pathologies." (PMID 33522967, 2021). "In addition, the investigation of Nlgn1 in tauopathies can provide information on the discriminatory power of Nlgn1 for different diseases, as possible diagnostic tool." (PMID 33522967, 2021). "ADNP showed relatively reduced expression in the ADNP syndrome cerebellum, which was also observed for 25 additional genes (representing >50% of the tested genes), including NLGN1, NLGN2, PAX6, SMARCA4, and SNAP25, converging on nervous system development and tauopathy." (PMID 32661233, 2020). "Nlgn1 levels could not discriminate between the different tauopathies." (PMID 33522967, 2021).
breast carcinoma (1 paper, 2023). "NLGN1, specifically, was described as an oncogene shown to be upregulated in NF1-associated breast cancer." (PMID 37770931, 2023).
bruxism (1 paper, 2024). Excessive clenching of the jaw and grinding of the teeth. "Considering that also bruxism could be caused by an alteration of the hippocampus-amygdala–hippocampus-prefrontal circuit, it can be speculated that variants within NLGN1 could be responsible for determining bruxism onset." (PMID 38397906, 2024). "Taking advantage of this approach, in this study, three novel candidate genes, i.e., NLGN1, RIMBP2, and LHFP, were identified as potential risk loci for bruxism." (PMID 38397906, 2024). "The first region was detected on chromosome 3, near the Neuroligin 1 (NLGN1) gene; individuals carrying the C allele of the most associated SNP, namely rs2046718, had a greater risk of developing bruxism than those with the T allele." (PMID 38397906, 2024).
cognitive decline (1 paper, 2020). "Moreover, the finding that NLGN1 level in the aMCI/AD hippocampus correlates with cognitive function supports the idea that synaptic dysfunction adequately predicts cognitive decline in AD1–3,22." (PMID 32332783, 2020).
colorectal adenocarcinoma (1 paper, 2022). The most common type of colorectal carcinoma. "We initially analyzed the expression of NLGN1 in a public CRC gene expression database (TCGA, PanCancer Atlas- Colorectal Adenocarcinoma) through the cBioportal platform." (PMID 36056393, 2022).
hyperopia (1 paper, 2008). A refractive error in which rays of light entering the eye parallel to the optic axis are brought to a focus behind the retina, as a result of the eyeball being too short from front to back. "Five of them were upregulated during induction of hyperopia with positive lenses (DCX, NLGN1, QSER1, TMTC3, and LOC41695) and one was downregulated (GRHL3)." (PMID 18769560, 2008).
ischemia (1 paper, 2023). A hypoperfusion of the BLOOD through an organ or tissue caused by a PATHOLOGIC CONSTRICTION or obstruction of its BLOOD VESSELS, or an absence of BLOOD CIRCULATION. "Specifically, we demonstrated early ischemia-induced decreases in the expression of PSD-95, neuroligin 1, and the NMDAR2B subunit, which agree with observations reported in previous studies." (PMID 37208551, 2023).
memory (1 paper, 2020). The activities involved in the mental information processing system that receives (registers), modifies, stores, and retrieves informational stimuli. "The absence of NLGN1 thus seems to increase the neurotoxicity of Aβo by inducing neuronal loss following an intermediate exposure (i.e., 4 days) whereas neuronal loss is generally obtained from longer exposure (i.e., 6 days) or higher doses, similar to memory deficits." (PMID 32332783, 2020).
myopia (1 paper, 2016). "Among the mRNAs targeted by differentially expressed miRNAs, there were several (Prkar1a, Rims2, Map2, Gabarapl1, Htr7, Add3, Erc1, Nlgn1) which were involved in synapse formation and function suggesting that synaptic function was one of the biological processes affected in form-deprivation myopia." (PMID 27622715, 2016).
Obesity (1 paper, 2024). Accumulation of substantial excess body fat. "Others among the top 10% high-scoring genes with an unknown role in the context of obesity include ERC2 (23.8), ZNF131 (23.8), NLGN1 (22.8), MLTT10 (22.8), RERE (22.8), and PDCH9 (22.8)." (PMID 38754426, 2024).
prostate tumour (1 paper, 2021). "Both our sci-ATAC-seq data and our cyclic IF results indicate NRXN1 and NLGN1 expression in immune cells infiltrating the prostate tumours." (PMID 34911933, 2021). "Our findings suggest the possibility that NRXN1 and NLGN1 expression and secretion in high-grade prostate tumours may modulate the activity between cancer cells and neurons, which may contribute to perineural invasion or neoneurogenesis in prostate cancer." (PMID 34911933, 2021). "Finally, we observe that both NRXN1 and NLGN1 are expressed in the N-CAM positive neuronal cells within the prostate tumour stroma, with overall slightly higher expression profiles in high-risk patients." (PMID 34911933, 2021).
traumatic stress disorder (1 paper, 2024). "Notably, a GWAS published in 2016 supported the potential involvement of the NLGN1 gene in post-traumatic stress disorder onset." (PMID 38397906, 2024).
tuberous sclerosis (1 paper, 2023). Hereditary disease characterized by seizures, intellectual disability, developmental delay, and skin and ocular lesions. "Since in Tuberous Sclerosis there is hyperactivation of mTORC1 and subsequently hyperphosphorylation of its downstream effectors, 4E-BPs and S6Ks, we reasoned that Nlgn1 mRNA translation might be increased in Tsc2+/− hippocampi." (PMID 37293130, 2023).
viral infection (1 paper, 2009). "The function for four targets have been ascribed (ROBO1, NLGN1, CPSF1, ATP8A1), but none of them have been linked with viral infection." (PMID 19788744, 2009).
cancer (11 papers, 2018 to 2024). A tumor composed of atypical neoplastic, often pleomorphic cells that invade other tissues. "Next, we performed in vitro and in vivo assays, demonstrating that NLGN1 promotes cancer cell invasion and migration along nerves." (PMID 35053395, 2022). "Then, using in vitro and in vivo tests, we were able to show that NLGN1 stimulates cancer cells to invade and move along nerves." (PMID 36499024, 2022). "Here, we investigate instead the potential pro-tumoral activities of NLGN1 with a specific focus on the relation that cancer cells take with nerves in order to grow and spread (a general phenomenon that we call tumor–nervous connections or TNCs)." (PMID 35053395, 2022). "We found that blocking GDNF activity with a specific antibody completely inhibited NLGN1-induced in vitro cancer cell invasion of nerves." (PMID 35053395, 2022). "Results show that NLGN1 is expressed by cancer cells of the primary tumor, by migrating “budding” tumoral cells, and by intravasated tumor emboli in human CRC samples." (PMID 36056393, 2022). "At the molecular level, the functional link between APC and NLGN1 in the cancer context was studied." (PMID 36056393, 2022). "As a cellular adhesion receptor, the role of NLGN1 in cancer cell migration through peripheral nerve fiber needs further investigation." (PMID 34340665, 2021). "Furthermore, in a highly interesting parallel with the central nervous system, cofilin appears to mediate NLGN1′s role in both synaptic plasticity and cancer cell movement." (PMID 35053395, 2022). "However, very few studies have been conducted to investigate NLGN1’s biological role specific to cancer." (PMID 34340665, 2021). "At the cellular level, our in vitro model of TEM is set up so that cancer cells encounter first the apical side of endothelial cells, mimicking extravasation, in line with the tail vein assay, which shows an increased ability of NLGN1 expressing cells to extravasate and colonize the lungs." (PMID 36056393, 2022).
neurodevelopmental disorder (9 papers, 2020 to 2025). A behavioral and cognitive disorder with onset during the developmental period that involves impaired or aberrant development of intellectual, motor, or social functions. "Notably, the mRNA levels of ASD‐related risk genes like NLGN1, SHANK2, SHANK3, and CNTNAP2 are influenced by the prenatal suppression of histone deacetylase family, which are linked to neurodevelopmental disorders." (PMID 37807632, 2023). "Therefore, previous studies on NLGN1, which are preferentially expressed in human brain, focus mostly on neurodevelopmental disorders." (PMID 34340665, 2021). "Overall, our study revealed that reducing Nlgn1 expression is a possible new therapeutic avenue for TSC and plausibly for other neurodevelopmental disorders." (PMID 37293130, 2023). "Thus, we demonstrate that reduction of Nlgn1 expression in Tsc2+/− mice is a new therapeutic strategy for TSC and potentially other neurodevelopmental disorders." (PMID 37293130, 2023).